CALR (calreticulin)
Diseases named in the same sentence as CALR in open-access papers (continued):
Sharing a sentence is not in itself a finding about the gene and the disease.
tumor (continued). "However, when we looked at potential DAMPs in 213Bi-treated MM cell supernatants, we could not detect any significant release of HMGB1, Hsp70, or TNFα or membrane expression of Hsp70, Hsp90, or calreticulin on irradiated tumor cells." (PMID 26539436, 2015). "Finally, a tumor-promoting role for Calreticulin has been shown to be linked to dysregulation of Cortactin expression, and vascular endothelial growth factor C (VEGF-C) contributes to tumor growth and metastasis via Src-miR326-mediated overexpression of Cortactin in ESCC." (PMID 26345720, 2015). "Interestingly, not only calreticulin on the plasma membrane, but also its overall expression is frequently enhanced in tumor tissue, potentially indicating that this chaperone could indeed provide an avenue for future cancer immunotherapy." (PMID 25386408, 2014). "This surface expression of calreticulin could mark the tumor cells for immune destruction." (PMID 24574359, 2014). "Based on its upregulation and, more importantly, its translocation to the cell surface across disparate tumor types in response to sublethal radiation, we hypothesized that surface calreticulin plays an additional role in IM as it pertains to increased CTL-mediated lysis." (PMID 24480782, 2014). "In the current study, we explored the combination of the DNA vaccine encoding calreticulin (CRT) linked to human papillomavirus type 16 (HPV-16) E7 antigen (CRT/E7) with the TLR7 agonist imiquimod for their ability to generate E7-specific immune responses and antitumor effects in tumor-bearing mice." (PMID 20426849, 2010). "Immunofluorescence staining indicated an elevation in the expression levels of calreticulin (CRT) and high-mobility group protein B1 (HMGB1) within tumor tissues following APPF+laser treatment, thereby promoting dendritic cells (DCs) maturation." (PMID 41355972, 2026). "Oncolytic viruses address this limitation by selectively replicating in tumor cells, inducing robust ICD characterized by four cardinal hallmarks: calreticulin exposure, ATP secretion, HMGB1 release, and type I interferon production." (PMID 42043250, 2026). "Simultaneously, our data also showed increased expression levels of heat shock proteins (HSPs), Calreticulin and HSP70, in the tumor cells post BNT162b2 treatments." (PMID 39743545, 2025). "Tumor cells also release adenosine triphosphate (ATP), high mobility group box 1 protein (HMGB1), and calreticulin, which are recognized by cell surface receptors P2X7, CD91, and toll-like receptor 4 (TLR4), respectively, on DCs." (PMID 41375050, 2025). "In contrast, exposure to dying tumor cells or immunogenic stimuli (e.g., DAMPs like HMGB1 and calreticulin) can transiently enhance phagocytosis." (PMID 40724825, 2025). "Combining CD47 inhibition with pro-phagocytic “eat-me” signals, such as calreticulin (CALR), can amplify macrophage-mediated clearance of tumor cells." (PMID 41179296, 2025). "By increasing the surface-bound immunogenic cell death marker levels, like calreticulin (CRT) and HSP70, the gas plasma treatment indirectly triggers the host antitumor immunity, e.g., enhanced tumor cell uptake by macrophages." (PMID 41345386, 2025). "On one hand, it can induce immunogenic cell death (ICD) in tumor cells, releasing DAMPs such as ATP, HMGB1, and calreticulin, which promote dendritic cell (DC) maturation and T cell activation, thereby enhancing anti-tumor immune responses." (PMID 41407677, 2025). "Significant green fluorescent signals were observed in the tumor tissues, indicating that HAQ/223Ra@HNPs successfully induced CALR exposure in the cell plasma membrane." (PMID 41320759, 2025). "Such dangers signals include the exposure of calreticulin (CALR) on the cell surface, the secretion of ATP, and the release of high mobility group box 1 (HMGB1), which collectively promote tumor-specific immune responses." (PMID 40635571, 2025).
tumor (continued). "Various key regulators (CALR, MSI2-Numb, ZNF263/ZNF31, and GINS2) play significant roles in promoting EMT following genomic alterations under different tumor microenvironment conditions." (PMID 39781447, 2025). "The combination of CALR nanotide-modified EcN-215 and ICG reshaps the tumor microenvironment (TME) by enhancing the infiltration of CD45+CD3+ T cells and CD11b+F4/80+ macrophages." (PMID 40688079, 2025). "This is followed by immunostimulatory DAMPs secreted by dying tumor cells such as passive release of HMGB1, calreticulin surface translocation, and ATP release that act on TLRs of DCs to promote their maturation." (PMID 41375050, 2025). "Fotoenticine has also demonstrated potential to induce ICD by exposing calreticulin and promoting the release of ATP and HMGB1, thereby stimulating the immune system against the tumor." (PMID 40916083, 2025). "Combined with the tumour sequencing data obtained from HCC-bearing mice and TCGA, these results suggest that ACADS specifically facilitates CALR expression." (PMID 39800718, 2025). "Under endoplasmic reticulum stress, calreticulin (CRT), a soluble protein in the endoplasmic reticulum, is translocated to the surface of tumor cells." (PMID 40051791, 2025). "ICD is characterised by calreticulin exposure, HMGB1 release, and activation of the cGAS-STING pathway, which together prime anti-tumour immunity." (PMID 41226343, 2025). "The infection of tumor cells with oncolytic adenoviruses induces markers of an immunogenic cell death (ICD), such as surface expression of CALR, representing a ‘eat-me’-signal for immune cells." (PMID 38357194, 2024). "Previous studies have shown that ICP regulators, such as PD-L1 and TIM3, and ICD regulators, such as CALR and HMGB1, play critical roles in regulating host anti-tumor immunity and thus affect the efficacy of mRNA vaccines." (PMID 38672082, 2024). "The chronology of DAMP emission demonstrated by HG-3 and OSU-CLL cells subjected to SpiD3 treatment—starting with ecto-CALR, followed by extracellular ATP and HMGB1 release—is concordant with studies in the literature characterizing ICD in other tumor models." (PMID 39767763, 2024). "This highlights the delicate balance between pro-phagocytic signals like CALR and anti-phagocytic signals such as CD47 in the immune system’s ability to recognize and eliminate tumor cells." (PMID 39682299, 2024). "Through the cGAS-STING pathway, DAMPs, such as calreticulin, ATP, and HMGB1, promote DCs and macrophages’ recognition of tumor antigens and facilitate the infiltration of CD8+T cells into tumors, thereby stimulating tumor immunity." (PMID 38853203, 2024). "Finally, they demonstrate an increase adsorption of prophagocytic signaling protein calreticulin and discuss how enhanced adsorption of calreticulin could benefit studies tailored toward increasing tumor-specific immune responses following chemotherapy/radiation." (PMID 38593053, 2024). "Calreticulin (CALR) is another kind of DAMP that can bind to CD91, promoting the DC maturation and phagocytosis of dying tumor cells." (PMID 38254708, 2024). "The findings revealed that C1 CALR+MCs, C2 ALOX5+MCs, C3 ANXA2+MCs, C5 IL32+MCs, myeloid cells, fibroblasts, and SMCs are capable of targeting tumor cells by releasing TWEAK." (PMID 39224598, 2024). "Immunofluorescence images of PDEH showed a significant improvement in calreticulin (CRT), indicating the induction of immunogenic cell death and inhibition of tumor growth." (PMID 39118566, 2024). "Our study examined the expression patterns of ICP like PD-L1 and TIM-3 and ICD modulators like CALR and HMGB1 in two ferroptosis subtypes to determine their effects on host anti-tumor immunity and mRNA vaccine efficacy." (PMID 39286654, 2024).
tumor (continued). "THT reduced tumor burden through cell death mechanisms, including upregulated ICD marked by calreticulin exposure within 48 hours." (PMID 39872527, 2024). "In comparison to the control group, calreticulin (CRT) and high mobility group box protein B1(HMGB1) expression were significantly higher in tumor tissue after combined treatment with Cu-LCP/DSF NPs and anti-PD-1." (PMID 38355548, 2024). "In other studies, T. cruzi calreticulin (rTcCRT) was documented to have anti-angiogenic and anti-tumor properties, inhibiting the growth of the murine mammary (TA3 MTXR tumor cell line) in vivo." (PMID 39367471, 2024). "This activation involves the release of DAMPs, such as calreticulin (CALR), HMGB1, adenosine triphosphate, and HSPs, from dead tumor cells." (PMID 38725632, 2024). "Tumor cells undergoing ICD provoke immunostimulatory effects owing to the exposure or release of DAMPs, such as heat shock proteins (HSPs), calreticulin (CRT), the high-mobility group box 1 (HMGB1) protein, and adenosine triphosphate (ATP)." (PMID 38017537, 2023). "Western blotting analysis showed the obviously higher contents of “eat me” signals CALR, HSP70 and HSP90 in the prepared ICD tumor cell membrane (IM) than those in the membrane vesicles of TC-1 cells without ICD induction, using Na+ K+/ATPase as a control." (PMID 37684628, 2023). "CMS5 tumor cells are more sensitive to the MMC treatment, as evidenced by a higher proportion of calreticulin and HMGB1-positive cells, compared to E.G7 tumor cells, which are more likely to undergo immunogenic cell death." (PMID 37631898, 2023). "The three genes (CALR, IFNB1, and IFNG) were involved in anti-tumor immunity, which improved the predictive performance of this signature." (PMID 38023241, 2023). "Among them, the actions of 6 tumor-suppressing proteins, ENO1, Ubiquitin C (UBC), Moesin (MSN), heat shock protein 90ab1 (HSP90ab1, aka HSP90β), Calreticulin (CALR), and Histone H4 (H4), have been documented with a proposed mechanism 12-14." (PMID 37056934, 2023). "The current analysis revealed that CALR was positively related to M1 macrophages, DCs, CD8+, and CD4+ memory T cells in tumor microenvironment; conversely, CALR was negatively correlated with M2 macrophages." (PMID 36907982, 2023). "To investigate the functional role of the CANX/CALR cycle in ITGA5/B1-mediated adhesion to FN, we used MIA PaCa-2 cells expressing an actin-chromobody tagged with GFP to analyze the spreading of tumor cells on FN-coated plates by live-cell imaging." (PMID 37563605, 2023). "Calreticulin (CRT) is an endoplasmic-reticulum-resident chaperone that functions as a DAMP and plays a crucial role in tumor antigen recognition." (PMID 37376141, 2023). "The higher calreticulin (CRT) exposure and release of high mobility group box 1 (HMGB-1) also act as an “eat-me” signal to induce tumor cell apoptosis." (PMID 37238966, 2023). "We validated our RNA-sequencing results by performing IHC on day fourteen tumor sections for markers of cell death (cleaved caspase-3) and DAMP release (HMGB1 or calreticulin)." (PMID 37090639, 2023). "We previously reported that histotripsy tumor ablation results in the widespread translocation of DAMPs like HMGB1 and calreticulin within the ablation zone." (PMID 36756111, 2023). "Furthermore, surface-exposed calreticulin (CALR), which interacts with LDL receptor-related protein 1 (LRP1), serves as a de novo uptake signal and facilitates DC-mediated phagocytosis of tumor cells, hence resulting into the transfer of tumor-associated antigens into antigen-presenting cells." (PMID 37907944, 2023). "High linear energy transfer helium ion therapy and carbon ion radiotherapy induce a high level of immunogenic cell death proteins such as calreticulin, HSP‐70, DNA and others which stimulates the cGAS/STING pathway for radiogenic tumor death." (PMID 36411943, 2023).
tumor (continued). "To assess the potential mechanism of tumor-suppressive action of PCOLCE and CALR, we conducted an immunoprecipitation assay." (PMID 36943734, 2023). "(H) Tumor selectivity, larger than 1 for CW008-treated MSC CM and calreticulin, indicating the selective inhibition of OS cells (TT2, U2OS, and MG63) compared to MSCs." (PMID 36943734, 2023). "TTFields can also induce immunogenic death of tumor cells, leading to the release of danger signals such as HMGB1, ATP, and calreticulin, which activate dendritic cells and promote CD45+ leukocyte enrichment." (PMID 37916157, 2023). "The oncolytic peptides DTT-205 and DTT-304 induced calreticulin exposure and HMGB1 release, promoting tumour remission and the development of long-term immune memory against sarcoma and lung cancer cells in vivo." (PMID 38077402, 2023). "The SDT process can also increase the expression of calreticulin (CRT) on the surface of tumor cells, stimulate the release of cytokines, and promote a specific anti-tumor immune response." (PMID 37569377, 2023). "A pro-phagocytic signal of CALR is counteracted by CD47, and blockage of CD47 is reported to induce in vivo tumor elimination by stimulating phagocytosis of cancer cells." (PMID 36943734, 2023). "Consistency between the proteomics data and tumor gene expression was also reported for the upregulation of FN1 and the downregulation of CALR and AKAP12 in the HR-NB patients compared to the LR-NB cases." (PMID 37947594, 2023). "TTFields can induce immunogenic death of tumor cells, leading to the release of danger signals such as HMGB1, ATP, and calreticulin, which activate dendritic cells and promote CD45+ leukocyte enrichment." (PMID 37916157, 2023). "For instance, ERS induced by thapsigargin or doxorubicin partially regulates the release and binding of calreticulin (CRT, an ER chaperone) to the surfaces of OC cells, where it releases an “eat me” signal and activates anti-tumor adaptive immune responses." (PMID 37817482, 2023). "The corresponding heat map further proved that HSP90B1 was positively correlated with the six genes (HSPA5, PDIA3, MANF, PDIA4, CALR, and PDIA6) in various tumours." (PMID 36291587, 2022). "On the one hand, IRE induced tumor cell necrosis and release of DAMPs including adenosine triphosphate (ATP), high mobility group box 1 (HMGB1) and calreticulin to stimulate anti-tumor immunity." (PMID 36505437, 2022). "ICD stimulates antitumor immunity by different effects on cancer cells, including the promotion of surface expression of calreticulin (CRT) and high-mobility group box 1 (HMGB1) in tumor cells and the increasing of adenosine triphosphate (ATP) secretion." (PMID 35335881, 2022). "The expression of calreticulin (CRT) and CD47 in the tumor was evaluated, as they are key signals for the innate immune response." (PMID 36176603, 2022). "The core regulatory mechanism describes the release of CALR, ATP, and HMGB1 molecules from dying tumor cells, and inner-state activation or evolution of immature DC, activated DC, migrating DC, lymph node DC, T cell, and cytotoxic T lymphocyte cell types." (PMID 37420422, 2022). "In ICD, injured cancer cells, in addition to releasing tumor antigens, release various danger signals including high mobility group box 1 (HMGB1), calreticulin (CRT), heat shock protein (HSP) 90, HSP 70, and adenosine triphosphate (ATP)." (PMID 35740662, 2022). "Here, knockdown of STAT3 altered calreticulin, ERp57, HSPs, and CD47 levels on the cell surface as well as the release of soluble mediators such as ATP, which stimulate the tumour antigen‐presentation ability of DCs and macrophages." (PMID 35665592, 2022). "Shannon Grabosch’s study demonstrated that cisplatin activated the cGAS-STING pathway to modify tumor immunogenicity by increasing PD-L1, MHC I and calreticulin in tumor cells." (PMID 35720348, 2022).
tumor (continued). "The exposure of calreticulin and the release of ANXA1, ATP and HMGB1 result in the attraction and maturation of DCs in the tumor microenvironment." (PMID 36015189, 2022). "The dying tumor cells release tumor antigens and adjuvant molecules (ATP, HMGB1, and ecto-calreticulin) that trigger the involvement of macrophages in the immune response." (PMID 36679900, 2022). "We also showed that probes ICAM1, calreticulin, PD-L1, neuropilin-1, galectin-3 and MPO were spatially associated with immunogenic cell death and, together with the enriched standard cell types, they might serve as an early predictive biomarker of induced anti-tumor immunity in situ." (PMID 35788566, 2022). "Recently, it has been reported that several molecules, including calreticulin, HMGB1, and ATP, released by tumor cells are responsible for chemotherapy-induced anticancer immune responses." (PMID 34733785, 2021). "Calreticulin is typically found in the lumen of the endoplasmic reticulum, but localizes to the plasma membrane in PDT-treated tumor cells, where it serves as an “eat-me” signal to antigen-presenting cells." (PMID 36405502, 2021). "NDV infection also induces a strong ICD in lung and glioblastoma cancer cells, observable by the elevated exposure of calreticulin, the release of HMGB1, ATP, and HSP79/90, and the induction of a long-term tumor-specific immune response." (PMID 34745965, 2021). "The authors showed that PDT triggers the exposure of CALR at the plasma membrane of CT26 mouse colon cancer cells in vitro and has an effective prophylactic tumor vaccination effect in syngeneic mouse models." (PMID 34834202, 2021). "CALR together with PDIA3 has been shown to translocate from the ER to the cell surface, leading to the recognition of the tumor by dendritic cells and then to T cell mediated eradication of the tumor." (PMID 34830970, 2021). "CALR, a characteristic antigen expressed on tumor cells undergoing ICD, is involved in the anti-tumor immune response." (PMID 34660305, 2021). "Our findings illustrate the role of CALR on the NSCLC cell membrane surface in promoting DC maturation, which provides insights on the role of CALR in anti-tumor immunity." (PMID 34660305, 2021). "A pilot of study indicated that the expression of HMGB1, calreticulin, and HSP70 in tumor cells increased significantly as the levels of electric field strength increased." (PMID 32508058, 2020). "In both in vitro and in vivo models, their nanostructure led to calreticulin translocation to the cell surface when excited by NIR lasers and increased the number of activated CD8 T cells in both the tumor and spleen in mouse models after treatment." (PMID 33260534, 2020). "After in situ ablation, the expression of Calreticulin (CRT), which is expressed on tumor cell surface and recognized as a critical role in antigen presenting process was significantly upregulated according to western blot and immunofluorescence assay." (PMID 32272956, 2020). "Anti-tumor immune response can be primed by ICD, a type of cell death characterized by cell-surface translocation of CALR, extracellular release of ATP and HMGB1." (PMID 32455811, 2020). "With co-delivery of PTX and IL-2 to the tumor region, the low-dosage of PTX release triggered the calreticulin (CRT) exposure on tumor cells and further induced the infiltration of CD8+ T cell into tumor tissue." (PMID 32210184, 2020). "Apart from the direct killing of tumor cells by IRE, the apoptosis of tumor cells is accompanied with the expression or release of DAMPs, including HMGB1, calreticulin, and HSP70, illustrating that IRE can also induce ICD of tumor cells." (PMID 32508058, 2020). "Interaction of CALR with LRP1 acts as an “eat-me” signal, which promotes tumor antigen uptake by immature DCs." (PMID 33281620, 2020).